SARM1 (sterile alpha and TIR motif containing 1)
Diseases named in the same sentence as SARM1 in open-access papers (continued):
Sharing a sentence is not in itself a finding about the gene and the disease.
glaucoma (15 papers, 2018 to 2026). Increased pressure in the eyeball due to obstruction of the outflow of aqueous humor. "Our data indicating that loss of Sarm1 affords protection of RGC in glaucoma agree with earlier studies that employed acute injury models to cause RGC death." (PMID 38331947, 2024). "Taken together, our data demonstrate that Sarm1 ablation reduces RGC loss in a rodent glaucoma model with chronic elevated IOP." (PMID 38331947, 2024). "Animal and cell culture data strongly implicate SARM1-dependent axon loss in some peripheral neuropathies, glaucoma, Parkinson disease, and other conditions, and human genetic studies support its involvement in rare axonopathies involving NMNAT2 mutation and in ALS." (PMID 35198877, 2022). "Thus Sarm1 deletion or inhibition may effectively reduce RGC loss in glaucoma and, given the scarcity of treatments for glaucoma, the potential of Sarm1 as a therapeutic target is intriguing." (PMID 38331947, 2024). "SARM1 is a compelling target for therapeutic intervention, as loss of SARM1 is profoundly protective in animal models of multiple neurodegenerative diseases including nerve injury, peripheral neuropathies, traumatic brain injury, glaucoma, retinitis pigmentosa, and Leber congenital amaurosis." (PMID 34779400, 2021). "The gene Sarm1 plays a key role in axonal degeneration and was recently implicated in RGC loss in glaucoma." (PMID 40371387, 2025). "It is possible MKK4/7 and/or JNK1/2/3 directly target NMNAT2 for degradation, ultimately triggering SARM1 activation and allowing axonal degeneration after glaucoma-relevant injury." (PMID 41397991, 2025). "Sarm1 KO can prevent degeneration in several neurodegenerative conditions, including glaucoma, traumatic brain injury, and peripheral neuropathy." (PMID 40344041, 2025). "Alternatively, it is possible that the observed reduction of RGC in eyes with glaucoma is the result of decreased neuroinflammation in Sarm1 KO mice." (PMID 38331947, 2024). "Our data elucidate a pivotal role for Sarm1 in RGC vulnerability in glaucoma and enhances our comprehension of its long-term effects within a chronic rodent model reflective of human pathology." (PMID 38331947, 2024). "Lastly, we touch upon potential therapeutic approaches targeting NMNATs and SARM1, as well as the nicotinamide trials for glaucoma." (PMID 38538779, 2024). "That the nerve lesioning experiments in our study found Sarm1 to drive axon destruction in both young and aged axons suggests it may still be a viable target for both juvenile (i.e. spinal muscular atrophy) and age-associated neurodegenerative disease (i.e. Parkinson’s, Alzheiemer’s, glaucoma)." (PMID 30010873, 2018). "Sarm1 KO has also been demonstrated to provide protection against retinal degeneration in glaucoma." (PMID 40344041, 2025). "Several research groups have also showed that SARM1 drives degeneration of RGCs and their axons after traumatic optic nerve injury, in a neuroinflammatory model of glaucoma, in the silicone oil-induced ocular hypertension, and after mitochondrial dysfunction and excitotoxicity." (PMID 38538779, 2024). "SARM1 becomes activated when the respective NMNAT is disrupted by mutation or (for NMNAT2) by axonal transport deficiency, underlying involvement of the pathway in LCA9 and glaucoma models respectively." (PMID 38538779, 2024). "Additionally, oligodendrocyte death is curbed in the Sarm1 KO mouse in a neuroinflammatory model of glaucoma." (PMID 37091921, 2023). "We previously developed a potent dominant negative SARM1 variant and demonstrated that AAV-mediated expression of dominant negative SARM1 strongly protects injured axons from degeneration in the peripheral nervous system and is also effective in a neuroinflammatory model of glaucoma." (PMID 33107823, 2020). "Taken together, these data suggest that attenuating Sarm1 activity through gene therapy, pharmacologic inhibition, or NAD+ supplementation, may be a novel therapeutic approach for patients with glaucoma." (PMID 38331947, 2024).
glaucoma (continued). "Even so, it is unlikely that neuroprotection is derived solely from SARM1 inhibition given that SARM1 KO in mice saves only retinal ganglion cell axons and not somas in glaucoma." (PMID 39180087, 2024). "Although Sarm1 KO mice clearly experienced less RGC loss than control mice in this glaucoma model, they are not completely protected, underscoring the fact that glaucoma is a multi-factorial disease." (PMID 38331947, 2024). "Another example of non-cell autonomous roles for SARM1 was recently shown in a model of glaucoma, where necroptosis signaling leads to the activation of SARM1." (PMID 36090788, 2022).
Parkinson disease (13 papers, 2017 to 2025). A progressive degenerative disorder of the central nervous system characterized by loss of dopamine producing neurons in the substantia nigra and the presence of Lewy bodies in the substantia nigra and locus coeruleus. "In experimental models of Parkinson’s disease, SARM1-deficient animals showed less degeneration of the axons of dopaminergic neurons compared to wild-type animals." (PMID 40433385, 2025). "In fact, Sarm1 is involved in induced Parkinson’s-Disease-like pathology and binds to PTEN-induced putative kinase 1 (PINK1), and its activity is L-type-Ca2+-channel-dependent." (PMID 38891076, 2024). "It has been reported that NMNAT2 depletion was related to SARM1-dependent axon degeneration in Parkinson's disease and other axonal disorders." (PMID 34758883, 2021). "SARM1 may be involved in the pathogenesis of Parkinson's disease by regulating immune responses and inflammatory processes and oxidative stress." (PMID 41018229, 2025). "SARM1 is also directly related to the development of Parkinson’s disease, a neurodegenerative disease characterized by the degradation of dopaminergic neurons in areas of the brain involved in movement control, mainly in the substantia nigra located in the telencephalon." (PMID 40433385, 2025). "The importance of SARM1 phosphorylation in the pathological process of Parkinson’s disease (PD) has not been determined." (PMID 37725528, 2023). "The detected alterations were specific and significant as the expression levels of NMNAT1, NMNAT2 and sterile alpha and TIR motif containing 1 (SARM1) were not significantly different in Parkinson’s disease patients compared to controls." (PMID 35397003, 2022).
viral infection (11 papers, 2020 to 2025). "The authors showed that the SARM1-mediated axon loss prevents the spread of virus along interconnected neurons, suggesting a possible host-defense mechanism restricting virus infection." (PMID 35493328, 2022). "This implies that SARM1 acts as a rapid facilitator of axonal degeneration in viral infection by causing accelerated digestion of NAD molecules, similar to its role in axonal injury." (PMID 32069324, 2020). "In recent years, there has been emerging evidence suggesting a contributory role of SARM1 in many neurodegenerative disorders, environmental neurotoxicity, and viral infections." (PMID 37002660, 2024). "This study also implicates a novel role of SARM1 mediated axonal degeneration in neurotropic viral infection." (PMID 32069324, 2020). "Importantly, the SARM1-DN rescue of strength defects was dependent on the extent of viral infection and transgene expression in the spinal cord, i.e., higher expression correlated with higher endpoint performance." (PMID 36287209, 2022). "Loss of axons can be followed by neuronal cell death, and there have been studies suggesting that SARM1 may be involved in neuronal apoptosis following oxygen deprivation, mitochondrial depolarization, and viral infection." (PMID 35507602, 2022). "Similarly, a recent study demonstrated that different field strains of lyssavirus (“rabies”) cause SARM1-dependent axon degeneration in CNS and PNS mouse neurons, further supporting a role of SARM1 in neurotropic viral infection." (PMID 35493328, 2022). "Moreover, RNA interference-mediated acute genetic loss of Nmnat2 may drive spontaneous degeneration due to the inherent additional cellular stress of this technique (e.g., viral infection) that synergizes with SARM1 activation." (PMID 40496808, 2025). "Moreover, SARM1 may be activated in the immune cells by cytotoxic T cells and may promote T cell death, thus either promoting viral infection or preventing excessive inflammation post infection." (PMID 38400192, 2024). "However, it is still to be determined whether upstream molecules triggering the activation of SARM1 in viral infection are the same as those activating axonal self-destruction in injury (axotomy) or trophic withdrawal." (PMID 32069324, 2020). "This adds on to previously established roles of SARM1 in innate immune response such as negative regulation of toll-like receptor (TLR3) signaling and induction of neuronal apoptosis in response to viral infection." (PMID 32069324, 2020). "Thus, the same biochemical function of SARM1 could lead to different immune outcomes depending on the context, an important point to keep in mind when considering the often conflicting roles of NAD+-consuming enzymes in viral infection." (PMID 34871367, 2021).
retinal degeneration (9 papers, 2020 to 2025). Degeneration of the retina. "Strikingly, Sarm1 deletion rescues photoreceptors and retinal degeneration caused by Nmnat1 deletion in mice, suggesting an involvement of SARM1 in the pathogenesis of LCA type 9." (PMID 38538779, 2024). "Given the importance of RPE function for photoreceptor health, and roles for SARM1 in non-neuronal cells we were interested to examine the effect of SARM1 deficiency on the RPE in a model of retinal degeneration that is thought to initiate with RPE loss." (PMID 35431772, 2022). "In support of this conjecture, recent studies found that SARM1 promotes retinal degeneration in X-linked retinoschisis and rhodopsin-deficient mice." (PMID 33107823, 2020). "This surprising result extends our understanding of both the mechanisms causing retinal degeneration and the potential role of SARM1 in human disease (Figley and DiAntonio, 2020; Coleman and Höke, 2020)." (PMID 33107823, 2020). "Similar to the data generated from tissue sections, gene dosage effects were also observed using this method to analyse retinal degeneration, with SARM1 loss significantly preserving retinal thickness at 6, 9, and 12 wk of age." (PMID 32312889, 2020). "In fact, the strong correlation we observed between OCT and H&E measurements over time lends further support to each individual method of measuring the rate of retinal degeneration and strengthens the observation that SARM1 deficiency slows the rate of degeneration." (PMID 32312889, 2020). "The objective of the study was to evaluate whether ablation of SARM1, a key component of the axon degeneration pathway, could protect against complex I deficiency, mitochondrial dysfunction and subsequent vision loss in a well-established chemically induced mouse model of retinal degeneration." (PMID 35163535, 2022). "Here we demonstrate the pro-degenerative role of SARM1 in photoreceptors is maintained in the NaIO3 model of retinal degeneration." (PMID 35431772, 2022). "This study reports that activation of SARM1 causes destruction of NAD pools in photoreceptor cells of the retina and identifies a role for SARM1-dependent photoreceptor cell death in retinal degeneration." (PMID 32312889, 2020). "Here, we demonstrate that overexpression of SARM1 can drive photoreceptor cell death in vitro, and that genetic deletion of SARM1 in the rho−/− model of retinal degeneration delays photoreceptor cell death in vivo." (PMID 32312889, 2020). "Overall, our data suggest that SARM1 can directly induce photoreceptor cell death, and that SARM1 has a role in facilitating photoreceptor cell death in the rho−/− model of retinal degeneration." (PMID 32312889, 2020). "The connection between SARM1, mitochondrial dysfunction, and retinal degeneration prompted us to investigate whether SARM1 drives RGC degeneration in ADOA." (PMID 40344041, 2025). "This current study aimed to characterise the effect of SARM1 deletion in an alternative model of retinal degeneration (RD) in which the retinal pigment epithelium (RPE) fragments following administration of oxidising agent, sodium iodate (NaIO3), leading to subsequent photoreceptor cell death." (PMID 35431772, 2022). "Our study adds to the growing body of data indicating that SARM1 inhibitors may also be of use in retinal degenerative diseases that have a SARM1 dependent component making SARM1 a potential therapeutic target of interest for future study in retinal degeneration." (PMID 35431772, 2022). "However, our data show that SARM1 activation is sufficient to drive degeneration of multiple types of retinal neuron (including RGC) in addition to photoreceptors, making SARM1 a promising target to treat retinal degeneration, at least in response to certain insults." (PMID 34870595, 2021).
retinal degeneration (continued). "While NMNAT1 gene replacement is a potential treatment option for LCA9, if SARM1 plays a more general role in retinal degeneration, then using gene therapy to express this dominant negative SARM1 could not only treat LCA9, but also multiple retinal neurodegenerative diseases." (PMID 33107823, 2020). "Hence, mutations in NMNAT1 may promote retinal degeneration through the direct impact on NAD+ biosynthesis and/or through the regulation of the SARM1-dependent degenerative program." (PMID 33107823, 2020). "Together these data indicate a pro-degenerative role for SARM1 in the photoreceptors, but not in the RPE, in an oxidative stress induced model of retinal degeneration consistent with its known degenerative role in neurons in a range of neurodegenerative settings." (PMID 35431772, 2022).
diabetic neuropathy (7 papers, 2021 to 2024). A chronic, pathological complication associated with diabetes mellitus, where nerve damages are incurred due to diabetic microvascular injury involving small blood vessels that supply these nerves, resulting in peripheral and/or autonomic nerve dysfunction. "In this study, we hypothesized that SARM1, an immune factor, was associated with diabetic neuropathy pathogenesis." (PMID 38400192, 2024). "Human genetic association with NMNAT2 and SARM1 strongly suggests aberrant activation of programmed axon death in polyneuropathies and motor neuron disorders, respectively, and animal studies suggest wider involvement including in chemotherapy-induced and diabetic neuropathies." (PMID 34595734, 2021). "The present study supports the presence of a correlation between SARM1 serum levels and diabetic neuropathy in T2DM patients when doses of COVID-19 vaccines were considered." (PMID 38400192, 2024). "Thus, a SARM1 inhibitor coupled with either NR or NMN may be more effective than a single agent alone in preventing or treating diabetic neuropathy." (PMID 38256175, 2024). "It was found that Sarm1−/− mice had no resistance to STZ-induced diabetes, but had resistance to STZ-induced diabetic neuropathy." (PMID 36292657, 2022).
Alzheimer disease (6 papers, 2020 to 2025). A progressive, neurodegenerative disease characterized by loss of function and death of nerve cells in several areas of the brain leading to loss of cognitive function such as memory and language. "SARM1 may be involved in the neuronal death process and may be associated with neuronal damage in Alzheimer's disease." (PMID 41018229, 2025). "This degeneration requires both the MAP3K Wnd/DLK and the NADase SARM1, both of which are well-known neurodegenerative actors linked to a range of central and peripheral nervous system diseases, such as chemotherapy-induced peripheral neuropathy (CIPN), ALS, and Alzheimer’s disease [39,]." (PMID 40505722, 2025). "In contrast, genes such as CTSH (which was also associated with Alzheimer disease) and SARM1 may make worthwhile therapeutic targets because they did not have genetically predicted effects on any of the other phenotypes after correcting for multiple testing." (PMID 32413284, 2020). "Our results of Sarm1 genetic inactivation advance white matter degeneration as a tractable therapeutic target for TBI and chronic traumatic encephalopathy, with potential application to other neurodegenerative diseases including Alzheimer’s disease and multiple sclerosis." (PMID 34001261, 2021).
diabetes (4 papers, 2021 to 2024). "In murine and diabetes and metabolic disease, inhibition of SARM1 prevents diabetic peripheral neuropathy and, in female mice, improves skeletal health." (PMID 38175722, 2024). "This further supports the consideration of bone quality and bone density as potential outcomes for future clinical trials of SARM1 inhibitors in settings of diabetes and beyond." (PMID 38175722, 2024). "In addition, this work supports the exploration of clinical SARM1 inhibition as a promising therapeutic strategy to promote neuroskeletal health in settings of diabetes and metabolic disease." (PMID 38175722, 2024). "Lastly, as vacor causes pancreatic β-cell destruction and diabetes in humans, these findings could also have broader implications, uncovering a role for SARM1 in the survival of insulin producing cells and aiding research on diabetes." (PMID 34870595, 2021). "Interestingly, Sarm1-/-mice are resistant to streptozotocin-induced diabetes." (PMID 38400192, 2024). "Several studies have reported on an association between SARM1 and DPN in animals; nonetheless, they did not evaluate the serum SARM1 levels in patients with diabetes to confirm its role in the disease." (PMID 38400192, 2024). "Beyond this, we found that prevention of SARM1-dependent DPN in males or the absence of DPN in WT females was not sufficient to mitigate the onset or progression of diabetic skeletal disease." (PMID 38175722, 2024).
Anxiety (3 papers, 2021 to 2026). Intense feelings of nervousness, tension, or panic often arise in response to interpersonal stresses. "Anxiety diverges by loading more strongly on inflammatory-apoptotic signaling, complement/sterile alpha and toll/interleukin receptor motif-containing protein 1 (SARM1)-linked axonal stress, and mitochondrial NAD-stress programmes." (PMID 42299234, 2026). "Taken together, these results suggested that SARM1 deletion in the CNS did not result in the anxiety or depression-like behavioral phenotypes." (PMID 37307837, 2024).
Atrophy (3 papers, 2021 to 2024). Any weakening or degeneration, especially through lack of use. "Furthermore, this may identify novel mechanisms by which global loss of Sarm1 promotes bone formation even in settings of severe metabolic disease and muscle atrophy." (PMID 38175722, 2024). "In this study, we have identified a similar, previously uncharacterised role for SARM1 in a model of RPE atrophy." (PMID 35431772, 2022). "Longitudinal MRI studies were conducted to advance the translational impact while further evaluating the effects of Sarm1 inactivation on white matter integrity and CC atrophy." (PMID 34001261, 2021). "Interestingly, the attenuation of photoreceptor cell death in the absence of SARM1 occurs despite the pace of RPE atrophy remaining apparently unaffected by the presence or absence of SARM1." (PMID 35431772, 2022).
brain injury (3 papers, 2021 to 2024). Acute and chronic (see also brain INJURIES, CHRONIC) injuries to the brain, including the cerebral hemispheres, CEREBELLUM, and brain STEM. "Notably, loss of SARM1 is protective in murine models of peripheral neuropathy and traumatic brain injury." (PMID 34184985, 2021).